SNHG30 (small nucleolar RNA host gene 30)
Synonyms: RP11-1094M14.11; formerly LINC02001
Gene: Long non-coding RNA gene on chromosome 17 (35,568,050 to 35,574,900, forward strand). Ensembl gene ENSG00000267321.
Gene Ontology:
Biological process: RNA processing
Cellular component: nucleolus
Diseases named in the same sentence as SNHG30 in open-access papers:
SNHG30 is named in the same sentence as 1 disease in open-access papers, as found by Europe PMC text mining. Sharing a sentence is not in itself a finding about the gene and the disease.
SNHG30 shares sentences with these, for which no sentence is quoted: prostate carcinoma (1 paper).